MGMT (O-6-methylguanine-DNA methyltransferase)
Diseases named in the same sentence as MGMT in open-access papers (continued):
Sharing a sentence is not in itself a finding about the gene and the disease.
glioma (continued). "Meanwhile, high-risk samples were also categorized as malignant glioma subtype like IDH wild-type gliomas, MGMT unmethylated gliomas, 1p19q non-codel gliomas, and mesenchymal/classical gliomas." (PMID 34603309, 2021). "In the meantime, high CI was related to high grade glioma, IDH wildtype glioma, 1p19q non-codeletion glioma, MGMT unmethylated glioma and aggressive subtype glioma." (PMID 34070840, 2021). "However, there are few studies on the relationship between the status of IDH, MGMT, TERT and perfusion indicators in glioma patients." (PMID 34814870, 2021). "Because the heightened expression or non-expression of MGMT plays a pivotal role in glioma therapeutics, we applied bioinformatics and experimental tools to identify the regulatory elements in the MGMT and neighboring EBF3 gene loci." (PMID 33801310, 2021). "Therefore, the role of PD-L1, PD-1 and their relationship with MGMT, IDH, VISTA, B7-H3 in glioma need specific deep more research." (PMID 34660294, 2021). "The MGMT promoter methylation can predict the TMZ therapy efficacy, and in many glioma subtypes which do not have MGMT promoter methylation, TMZ does not improve patients’ outcome." (PMID 34084145, 2021). "The nomogram established based on preoperative SIRI, age, extent of resection, number of gliomas, MGMT methylation status and histological types (only in grade III gliomas) could predict the prognosis more accurately." (PMID 34055639, 2021). "Furthermore, compared with those in the control and empty vector cells, FOXD2-As1 overexpression significantly reduced the ratio of methylated MGMT promoter DNA and promoted MGMT protein expression in TMZ-resistant glioma cells." (PMID 34739394, 2021). "In the present study, we demonstrate a novel mechanism that does not depend on MGMT expression in gliomas." (PMID 34256854, 2021). "Therefore, we only drew a nomogram in grade IV gliomas covering preoperative PNI, age, extent of resection, number of gliomas, and MGMT methylation status and evaluated the predictive effect of the nomogram." (PMID 35096561, 2021). "As with IDH mutation, the G-CIMP phenotype is also closely associated with methylation of the O6-methylguanine-DNA methyltransferase (MGMT) promoter, irrespective of glioma grade." (PMID 33673213, 2021). "CALD1 expression was increased in high grade glioma, IDH wildtype glioma, 1p19q non-codeletion glioma, MGMT unmethylated glioma and aggressive subtype glioma." (PMID 34070840, 2021). "The status of MGMT promoter was demonstrated as a factor to predict TMZ sensitivity, and the MGMT promoter unmethylation type glioma was not sensitive to TMZ." (PMID 34373835, 2021). "Gliomas with unmethylated MGMT, IDH WT, 1p19q non-codeletion, higher grade, and mesenchymal gliomas with poor survival outcomes had high TME-scores." (PMID 34489938, 2021). "Although multiple factors, such as upregulated expression of MGMT and multidrug resistance proteins, were reported to limit the toxicity of TMZ in glioma cells, emerging evidence has revealed that autophagy plays a crucial role in protecting glioma cells against TMZ treatment." (PMID 33879840, 2021). "Furthermore, we performed integrated analysis of molecular key hallmarks in glioma (IDH, TERT, MGMT methylation) and PD-L1 expression." (PMID 33963441, 2021). "In the TMZ‐resistant glioma xenograft model, treatment with JSH‐23 (an NF‐κB inhibitor) and lomeguatrib (an MGMT inhibitor) could enhance the sensitivity of the transplanted tumor to TMZ." (PMID 33460245, 2021). "Patients in Cluster 1, with worse survival, had higher level of IDH WT, 1p19q noncodeletion, and MGMT promoter unmethylation that all correlated with a more malignant phenotype of glioma." (PMID 33959130, 2021).
glioma (continued). "To summarize, perfusion parameters of glioma maybe related to the degree of tumor malignancy and the status of IDH, MGMT and TERT." (PMID 34814870, 2021). "However, O6-methylguanine DNA methyltransferase (MGMT) is capable of repairing cytotoxic groups and is the prevalent reason for TMZ resistance in glioma patients." (PMID 34202078, 2021). "CD74 was highly expressed in grade IV, IDH wildtype, 1p19q non-codeletion, and MGMT unmethylated gliomas." (PMID 34540893, 2021). "High FeAS GBM samples are also associated with malignancy clinical features (like wildtype IDH gliomas, non-codel 1p19q gliomas, and unmethylated MGMT gliomas)." (PMID 35126346, 2021). "We noticed that O-methylguanine-DNA methyltransferase (MGMT) is an important biomarker for the chemosensitivity of gliomas, and methylation detection (not IHC) is more precise for the clinical testing of MGMT in glioma patients." (PMID 33663520, 2021). "Perfusion analysis showed a tendency toward higher values in patients with unmethylated MGMT promoter but did not allow for significant differentiation of methylated vs. unmethylated gliomas (p > 0.05)." (PMID 34671241, 2021). "In addition, univariate and multivariate Cox regression analyses showed SAMD9, together with classical malignancy features of glioma (gender, age, WHO grade, IDH status, 1p/19q status, MGMT promoter status, radiotherapy, and chemotherapy)." (PMID 33936093, 2021). "To interrogate the translational significance of CCL5-CCR5 signaling in gliomas, we investigated a low-grade glioma (LGG)-GBM cohort from TCGA database with tumor grades, histology, subtypes and O6-methylguanine-DNA-methyltransferase (MGMT) promoter methylation information." (PMID 34239070, 2021). "Therefore, combined treatment with an NF‐κB/MGMT inhibitor and TMZ enhances the therapeutic efficacy of the latter in RIP2‐positive TMZ‐resistant glioma." (PMID 33460245, 2021). "These suggest that the favorable outcomes observed in MGMT-methylated grade III gliomas seem to be irrespective of treatment regimes." (PMID 32005184, 2020). "It appears that MGMT promoter methylation in both AA and GBM groups gives better survival when compared to those of without MGMT promoter methylation, points its important role as prognostic factor in glioma cases." (PMID 33282092, 2020). "In glioma WHO grade II, it is unclear whether the extent of MGMT promotor methylation and its prognostic role is independent from other molecular markers." (PMID 33184319, 2020). "Methylation of the MGMT promoter is seen as lower in frequency at around 35–45% of the cases of malignant gliomas (WHO grades III and IV), while it appears in approximately 80% of low-grade gliomas (WHO grade II)." (PMID 33552543, 2020). "MGMT promoter methylation has been detected in plasma ctDNA of glioma patients, and methylation status correlated with GBM tissue, suggesting that liquid biopsy material could have potential in detecting MGMT promoter methylation status." (PMID 32650387, 2020). "Comparison of DWI histogram profiles between low-grade gliomas with and without MGMT promotor methylation." (PMID 32158691, 2020). "In this study, we found that the mutant genes in the metastatic brain tumors included ALK, MDM2, ATM, BRCA1, FGFR1, and KRAS, and there were no glioma-related mutant genes (MGMT, IDH1, IDH2, 1p/19q, BRAF, and TERT)." (PMID 32973641, 2020). "The role of nonimaging biomarkers in gliomas and GBMs is well known, i.e., IDH1 mutation and methylguanine-DNA methyltransferase (MGMT) promoter methylation." (PMID 33072586, 2020).
glioma (continued). "Interestingly, we observed a general decrease in promoter DNA methylation of RASSF1A with increasing glioma malignancy (this effect was also observed to a lesser extent for SFRP1, MGMT, and RUNX3)." (PMID 32783304, 2020). "The accumulation of BMDMs in the TME of IDH1 WT glioma was O6-independent of the methylation status of the O6-methylguanine DNA methyltransferase (MGMT) promoter." (PMID 33374253, 2020). "Valproic acid, an effective antiepileptic drug, exerts a potential anti-GBM effect via the inhibition of angiogenesis and the downregulation of 0-6-methylguanine-DNA methyltransferase (MGMT) expression, which has been found to decrease CD44 expression in several glioma cell lines." (PMID 33322363, 2020). "For example, on the basis of mutations in the genes encoding the isocitrate dehydrogenases IDH1 and IDH2, co-deletion of 1p19q (oligodendroglioma) and methylation of O6-Methylguanine-DNA methyltransferase (MGMT) have been subclassified as molecular diagnostics and prognostic markers for gliomas." (PMID 33228738, 2020). "In our study, patients in the high-risk group had primary gliomas, exhibited GBM histology, high-grade, advanced age, IDH wild type, 1p/19q non-codeletion, and MGMT promoter un-methylation." (PMID 33330074, 2020). "Additionally, preclinical and clinical studies are required to provide convincing evidence showing that inhibition of MPG alone or in combination with the MGMT inactivation enhances TMZ activity and produces a clinical benefit for patients with gliomas." (PMID 33335215, 2020). "Independent of the promotor methylation status, some gliomas have MGMT gene alterations and genomic rearrangement leading to MGMT overexpression and TMZ resistance." (PMID 33137926, 2020). "Univariable cox regression identified the presence of MGMT promoter methylation (p = 0.013), 1p19q co-deletion (p = 0.014), younger age and surgical excision as potential predictors of longer survival in grade III gliomas." (PMID 32005184, 2020). "Textural features, which can quantify the intra-tumor heterogeneity by evaluating the gray-level intensity and position of the pixels within an image, have also been applied to predict MGMT methylation status, EGFR expression, and immune cell infiltration status for gliomas." (PMID 30719536, 2019). "To gain further insight into the predictive value of these biomarkers in molecular subgroups of gliomas, we analyzed the effect of EGFR amplification, PTEN deletion and MGMT promoter methylation in the response to therapy using the only group with representative samples - GBM IDH-wildtype." (PMID 31623593, 2019). "Patients with high-grade gliomas harboring deletions of chromosomes 9p and 10q may benefit more from TMZ treatment, and the MGMT resides on chromosome 10q." (PMID 31611911, 2019). "Temozolomide (TMZ) is the first-line chemotherapy drug for glioma, but whether TMZ should be withheld from patients with GBMs that lack O6-methylguanine-DNA methyltransferase (MGMT) promoter methylation is still under debate." (PMID 31611911, 2019). "Besides, a six-CpG signature based on MGMT and G-CIMP methylation status robustly predicted OS of gliomas in a treatment-independent manner." (PMID 31708732, 2019). "New tumor microenvironment-derived subtypes of GBM and new markers related to epigenetic changes, such as the promoter methylation status of the DNA repair enzyme, O6-methylguanine-DNA-methyltransferase (MGMT), have been added to the pool of known markers of the glioma progression." (PMID 31824268, 2019). "For instance, changes (e.g., mutation and methylation) in the serum DNAs (ctDNAs), such as MGMT 7-9, EGFR 10, and PTEN 9, have been proven to be effective biomarkers of glioma and may have the potential for the diagnosis of glioma." (PMID 31410219, 2019).
glioma (continued). "Of note, TERT mutations have a prognostic role in gliomas, being a negative prognostic factor in primary GBM without MGMT methylation." (PMID 30984267, 2019). "A distinct arrest and reduction in the proliferation was seen in methylated MGMT (GSC_CL1) compared with the nonmethylated MGMT (GSC_CL2) glioma cell type." (PMID 31249133, 2019). "This study retrospectively investigated the radiomics characteristics of gliomas by 18F-FDG-PET to build a conceivable model for predicting the MGMT promoter methylation status and patient prognosis noninvasively." (PMID 31426864, 2019). "Additionally, a combination assay of PP7 with temozolomide (TMZ), the most used chemotherapy for glioma patients, was performed resulting in synergism, while PP7 reduced TMZ resistance through inhibition of MGMT expression." (PMID 31814867, 2019). "In line, in this study all IDHmt 1p/19q codel LGG, and almost 90% of the IDHmt non-codel glioma were MGMT methylated." (PMID 29368212, 2018). "TMZ and ionizing radiation have been reported to increase AT101-induced cell death by autophagy in U343 (MGMT negative) and U87 (MGMT positive) glioma cells." (PMID 30486451, 2018). "The median age at diagnosis of adult H3 K27M-mutant gliomas was 32 years, with a midline location (spinal cord, thalamus, brainstem, or cerebellum); at molecular level, these tumors had a low rate of MGMT promoter methylation and lacked EGFR amplification." (PMID 30279357, 2018). "Activation of mTORC2 and thus SGK1-phosphorylated NDRG1 is increased in temozolomide resistant glioma cell lines and NDRG1 expression is elevated in tissues specimens from glioma patients, suggesting that this is mechanistically important for MGMT-conferred resistance to alkylating therapeutics." (PMID 29301334, 2018). "Interestingly, our results found that TMZ inhibits glioma cell proliferation, which was sufficiently pronounced to induce TMZ resistance via the upregulation of MGMT, which requires glycogenolysis." (PMID 30131700, 2018). "The MGMT methylation score was significantly higher in the codeleted than in the non-codel IDHmt glioma in all four datasets." (PMID 29368212, 2018). "A definitive cut-off for MGMT promotor methylation at the CpG position of 8% in pituitary adenomas, like in glioma cell lines, has not been defined to date." (PMID 29344904, 2018). "As responsiveness to TMZ differs in various cells, we used two glioma cell lines known to differ in sensitivity to TMZ due to the presence or absence of the MGMT protein." (PMID 30450051, 2018). "There were no expressional differences of P2RY12 between gliomas with or without MGMT promoter methylation." (PMID 28073370, 2017). "Here, we investigated whether the MMR pathway were involved in XIST/miR-29c regulation of glioma cell chemoresistance to TMZ by measuring the protein levels of MSH6, MGMT, and SP1." (PMID 28831025, 2017). "TMZ, on the other hand, was tested to be non-inferior to RT in elderly patients with a methylated MGMT-promotor in the NOA-08-Trial: The efficacy of RT did not depend on the MGMT-status of the treated high grade gliomas." (PMID 28454549, 2017). "In comparison of BICD1 with MGMT expression in predicting the overall survival of glioma patients by the Kaplan-Meier survival analysis, high BICD1 expression showed more significant impact (P<0.000001) than high MGMT expression (P=0.00003) on worse overall survival in the TCGA GBMLGG cohort." (PMID 29371945, 2017). "Recent evidences suggest that MET is able to i) modulate anabolic metabolism, inducing cell cycle arrest and cell death; ii) reduce GSC cells, increasing the treatment sensitivity and iii) improve responsiveness of glioma cells to TMZ treatment, counteracting the MGMT presence." (PMID 29348889, 2017). "In the current study, MGMT promoter methylation data were not available for most of the glioma patients." (PMID 28968983, 2017).
glioma (continued). "Regarding the glioma report, the authors speculated that APE1 operates in conjunction with other DNA repair molecules, such as NBN, PMS2, MGMT and PTEN, to influence biological and clinical outcomes in glioma." (PMID 28938675, 2017). "Consequently, when considering the use of DAC for gliomas, one has to take into account the impact of DAC on the MGMT methylation status." (PMID 27579489, 2016). "Glioma cells grown in these 3D cultures exhibited morphological and biochemical differences compared with cells grown in conventional 2D cultures, including enhanced chemotherapy resistance, GSC enrichment and MGMT overexpression." (PMID 27486877, 2016). "In a multivariate Cox regression model, methylation of MGMT promoter of high-grade gliomas analyzed by HRM, but not MSP, was found to be an independent predictive marker for OS." (PMID 27158275, 2016). "MGMT methylation is a marker of poor prognosis in human glioma, without treatment with an alkylating agent." (PMID 26967246, 2016). "Since the MGMT promoter methylation status analyzed by HRM is most precise in determining the patient’s outcome, we recommend HRM as a feasible and reliable method for routine diagnostics of high-grade glioma patients." (PMID 27158275, 2016). "Both intra-tumoral and temporal heterogeneity in MGMT status have been reported in some but not all such investigations in glioma." (PMID 25785247, 2015). "Possibly because of these limitations, the reliability of immunohistochemistry of MGMT protein to predict response to alkylating agents in glioma has been strongly criticized and not widely utilized in clinical practice." (PMID 26035292, 2015). "Two of the glioma cell lines SDT-3 and J3G-Bg showed high MGMT mRNA expression." (PMID 29061931, 2015). "Methylation of the MGMT promoter makes the cells more sensitive to alkylating drugs as was demonstrated in different type of cancer, not least gliomas." (PMID 25823555, 2015). "Moreover, BMPs increase GIC responsiveness to chemotherapy through downregulation of MGMT and low BMP levels are prognostic for poor survival in human glioma." (PMID 24877113, 2014). "This glioma cell line expresses very low levels of MGMT, which is confirmed by the absence of MGMT protein when visualised by Western blotting." (PMID 24909675, 2014). "Because the methylation status is not uniform in glioma tissue, it is important to characterize the intratumor heterogeneity of MGMT promoter methylation." (PMID 25175833, 2014). "Furthermore, in our previous paper we found that either high constitutive NF-kB activity in gliomas or ectopic p65 stimulated significant cellular resistance to the alkylating agent BCNU, through induction of MGMT expression." (PMID 25460932, 2014). "The study clearly demonstrates that in patients with recurrent high-grade glioma treated with either TMZ or PCV, IDH1/2 mutation and MGMT methylation levels are of prognostic value independent of tumour grade and of other clinical prognostic factors." (PMID 24952577, 2014). "In total 148 genes are located on 10q25.2-qter, including MGMT, DMBT1 and ERCC6, while the usual suspect, PTEN, is located more proximal to the centromere and is preferentially lost in higher grade gliomas." (PMID 25245118, 2014). "Further, irrespective of MGMT promoter methylation status, the prognosis of glioma patients can be improved if total resection is performed." (PMID 24160898, 2013). "In addition to MGMT, we studied ABCB1 promoter methylation because ABCB1 is significantly expressed in glioma and discussed as a potential resistance factor." (PMID 24380367, 2013). "Similarly, miR-221/222, induced downregulation of MGMT in LN428 cells, another TMZ-resistant glioma cell line, and in A375 cells, a TMZ-resistant melanoma cell line." (PMID 24147153, 2013).